MIR3613 (microRNA 3613)
Synonyms: hsa-mir-3613
Gene: MicroRNA gene on chromosome 13 (49,996,415 to 49,996,501, reverse strand). Ensembl gene ENSG00000264864.
Diseases named in the same sentence as MIR3613 in open-access papers:
MIR3613 is named in the same sentence as 2 diseases in open-access papers, as found by Europe PMC text mining. Sharing a sentence is not in itself a finding about the gene and the disease. The quoted sentences say what the papers report.
breast carcinoma (1 paper, 2021). "On the one hand, differentially expressed genes and enriched signaling pathways were analyzed in two groups of breast cancer patients divided according to MIR3613 CNVs from TCGA dataset (group of MIR3613 CNV ≥ 0, n = 586; group of MIR3613 CNV < 0, n = 492)." (PMID 33494814, 2021). "The proportion of MIR3613 deletions in TCGA breast cancer cohort was then studied using the UCSC Xena database." (PMID 33494814, 2021). "In this study, we found that MIR3613 locus was frequently deleted in breast cancer tissues depending on whole exome sequencing data from The Cancer Genome Atlas (TCGA)." (PMID 33494814, 2021). "Nearly 46% of TCGA breast cancer tumor samples were subjected to either heterozygous or homozygous deletions at MIR3613 locus and approximately 42% of breast cancer cell lines from Cancer Cell Line Encyclopedia (CCLE) showed copy number deletions of MIR3613." (PMID 33494814, 2021). "Further analysis demonstrated that the expression of cell cycle-related genes (CDC6, CDC25A, CDK1, ATM, E2F1, and MKI67) were much higher in breast cancer patients of 3 target genes high expression group or MIR3613 deletion group compared with their counterpart, respectively." (PMID 33494814, 2021). "It is noteworthy that NEAT1 was decreased and SNHG16 was increased in breast cancer samples with MIR3613 deletion compared to the non-deletion group from TCGA breast cancer cohort." (PMID 33494814, 2021). "Interestingly, MIR3613 locus (13q14.2) located near tumor suppressor genes RB1 (13q14.2) and BRCA2 (13q13.1) on chromosome 13 and copy number of this gene segment in breast cancer was frequently altered." (PMID 33494814, 2021). "We then analyzed the transcripts of differentially expressed genes in two groups of breast cancer patients divided according to MIR3613 CNVs from TCGA dataset (group of MIR3613 CNV ≥ 0, MIR3613 non-deletion, n = 586; group of MIR3613 CNV < 0, MIR3613 deletion, n = 492)." (PMID 33494814, 2021).
cancer (1 paper, 2021). A tumor composed of atypical neoplastic, often pleomorphic cells that invade other tissues. "The locus of MIR3613 was significantly deleted across 13 diverse cancer types including breast invasive adenocarcinoma." (PMID 33494814, 2021).